NOP9 (NOP9 nucleolar protein)
Synonyms: C14orf21; HP08474
Tractability: PROTAC: ubiquitination databases record sites on it; its protein half-life has been measured.
Gene: Protein-coding gene on chromosome 14 (24,299,850 to 24,309,124, forward strand). Ensembl gene ENSG00000196943.
Subcellular location (Human Protein Atlas): Nucleoplasm; Cytosol; Nucleoli
Gene Ontology:
Molecular function: RNA binding
Biological process: endonucleolytic cleavage in 5'-ETS of tricistronic rRNA transcript (SSU-rRNA, 5.8S rRNA, LSU-rRNA); endonucleolytic cleavage in ITS1 to separate SSU-rRNA from 5.8S rRNA and LSU-rRNA from tricistronic rRNA transcript (SSU-rRNA, 5.8S rRNA, LSU-rRNA); endonucleolytic cleavage to generate mature 5'-end of SSU-rRNA from (SSU-rRNA, 5.8S rRNA, LSU-rRNA); ribosomal small subunit export from nucleus
Cellular component: 90S preribosome; preribosome, small subunit precursor
Genetic constraint (gnomAD): Loss-of-function variants: 50 observed, 65.64 expected, observed/expected ratio (o/e) 0.76, 90% interval 0.61 to 0.96. The upper end of that interval is the gene's LOEUF score, 0.96, which puts it in group 4 of 6, group 1 being the genes least tolerant of losing a copy. Missense variants: 758 observed, 840.76 expected, observed/expected ratio (o/e) 0.9, 90% interval 0.85 to 0.96. Synonymous variants: 343 observed, 347.52 expected, observed/expected ratio (o/e) 0.99, 90% interval 0.9 to 1.08.
Homologues: Orthologues: chimpanzee NOP9 (99% identical), macaque NOP9 (96% identical), rabbit NOP9 (89% identical), pig NOP9 (87% identical), dog NOP9 (87% identical), guinea pig NOP9 (85% identical), rat Nop9 (82% identical), mouse Nop9 (82% identical), tropical clawed frog nop9 (46% identical), Drosophila melanogaster CG11123 (25% identical), Caenorhabditis elegans ZK792.5 (17% identical).
Diseases named in the same sentence as NOP9 in open-access papers:
NOP9 is named in the same sentence as 2 diseases in open-access papers, as found by Europe PMC text mining. Sharing a sentence is not in itself a finding about the gene and the disease. The quoted sentences say what the papers report.
neurological disorders (1 paper, 2020). "The NOP9 protein is linked to RNA-binding proteins, which have been associated with multiple neurological disorders." (PMID 33186502, 2020).
NOP9 also shares sentences with these, for which no sentence is quoted: cancer (1 paper).